Y_RNA (Y RNA )
Gene: Miscellaneous RNA gene on chromosome 16 (16,314,112 to 16,314,211, reverse strand). Ensembl gene ENSG00000206706.
Homologues: Orthologues: chimpanzee Y_RNA (98% identical), macaque Y_RNA (93% identical), dog Y_RNA (80% identical), pig Y_RNA (80% identical). Paralogues in human: Y_RNA (100% identical), Y_RNA (98% identical), Y_RNA (84% identical), Y_RNA (83% identical), Y_RNA (82% identical), RNY3 (81% identical), Y_RNA (81% identical), RNY3P1 (80% identical), RNY3P4 (80% identical), Y_RNA (80% identical), RNY3P11 (79% identical), Y_RNA (79% identical), and 92 more.